TLR2 (toll like receptor 2)
Diseases named in the same sentence as TLR2 in open-access papers (continued):
Sharing a sentence is not in itself a finding about the gene and the disease.
leptospirosis (continued). "We observed increased TLR2 gene expression in non-human cell lines, human polymorphonuclear cells, human neutrophils, and lung tissues obtained from patients who died because of leptospirosis." (PMID 39729468, 2024). "Considering the crucial roles of TLR2 and TLR4 in protecting against leptospirosis and recognizing the potent adjuvant effects of MPLA, it was of interest to assess the adjuvant potential of the naturally less toxic Leptospira LPS, specifically lipid A, against leptospirosis." (PMID 38140228, 2023). "Therefore, in the present study, we hypothesized and showed that pretreatment with CL429, a chimeric TLR2/NOD2 agonist, could mimic the protective effect observed with L plantarum and alleviate the acute phase of leptospirosis due to innate immune memory." (PMID 31107928, 2019). "Even though increased TLR2 expression in in-vivo and in-vitro studies was evident, human studies reported mixed results showing that the postulated effect of TLR2 response based on other studies may not be valid for human leptospirosis." (PMID 39729468, 2024). "After confirming the ability of leptospiral LPS to prime immune responses through TLR2-dependent signaling, we next asked whether any of the positive or negative regulators of the TLR-signaling cascade could be used as biomarkers for the diagnosis of leptospirosis." (PMID 32669469, 2020). "Accordingly, it was recently shown that L. interrogans serovar Autumnalis strain 56606v, which possesses an LPS atypically devoid of TLR2 activity and signaling only through TLR4, leads to a self-resolving leptospirosis and does not induce kidney colonization in mice." (PMID 32790743, 2020). "Aside from TLR2 and TLR4, other TLRs that have not yet been studied in the context of leptospirosis, such as TLR5 that senses flagellin, and TLR9, the receptor of bacterial DNA, could in theory be involved in the murine defense against L. interrogans." (PMID 24498450, 2014). "Moreover, TLR2 but not TLR4 is responsible for recognizing leptospiral lipopolysaccharide (LPS), the major inducer of inflammatory reactions and immune responses during leptospirosis." (PMID 28700741, 2017).
parasitemia (30 papers, 2008 to 2025). "Deficiency of TLR2 leads to uncontrolled first wave of parasitemia and acute death in an otherwise relatively resistance C57BL/6 mice." (PMID 31824484, 2019). "Infected TLR2 deficient mice on the relatively resistant background developed higher and uncontrolled first wave parasitemia compared to WT mice and died within 10 days post-infection." (PMID 31824484, 2019). "Both liver parasite burden and blood parasitemia were compared among WT, TLR2-, TLR4- and MyD88-deficient mice following intravenous P. yoelii sporozoite challenge." (PMID 26667391, 2015). "Consistent with the liver parasite burden, the level of parasitemia in TLR2-deficient mice was also significantly higher than that of WT mice during the course of infection." (PMID 26667391, 2015). "A previous study has suggested the association between TLR-2 and B10 in parasite infection." (PMID 30355335, 2018). "Once again in another murine study, TLR2 seemed to have an active role in the control of cutaneous leishmaniosis since TLR2-deficient mice presented an exacerbation of the pathology and parasitemia through promotion of the Th2 immunity in L. major and Leishmania mexicana infections." (PMID 28288677, 2017). "The neutralization of TLR4 in tlr2-/- macrophages completely abolished induction of IFN-β gene expression upon parasite infection, indicating an additive role for both TLRs." (PMID 35154115, 2022). "Previous studies found that TLR2 was upregulated when exposed to extracellular vesicles, soluble antigens, and glycosylphosphatidylinositols (GPIs) from N. caninum or parasite infection and regulated the secretion of a variety of cytokines." (PMID 34900761, 2021). "TLR2−/− mice on the usually resistant background were unable to control their first wave of parasitemia and succumbed acutely to the infection within 8–10 days post-infection." (PMID 31824484, 2019). "TLR2 also participates in the host defense against parasite infection such as T. gondii and T. cruzi." (PMID 28979269, 2017). "TLR2 can be activated by glycosylphosphatidylinositols (GPIs) presented on some protozoa and participates in the host defense against parasite infection, such as Toxoplasma gondii and Trypanosoma cruzi." (PMID 28979269, 2017). "We therefore explored using Pam2CSK4 (Pam2) and Pam3CSK4 (Pam3) lipopeptide adjuvants, which activate TLR2/6 and TLR2/1 heterodimers respectively, in vaccine models for parasitic infections." (PMID 26897363, 2016). "In this regard, the role of TLRs has been investigated; TLR9 was shown to be crucial in the parasitemia control and mouse survival, whereas TLR2 was defined as immunoregulator." (PMID 23650544, 2013). "This was the first study to reveal that PAD4 and TLR2 were found to be involved in the development of parasite-induced METs, thus providing guidance for further research on the mechanisms of host innate immunity against parasitic infection." (PMID 40598534, 2025). "Next, we investigated whether TLR2 plays a critical role in the outcome of infection by comparing parasitemia and survival period of T. congolense-infected WT and TLR2−/− mice." (PMID 31824484, 2019). "Overall, this study revealed that TLR-2 signaling was required for B10 induction mediated by EgPSC-ESPs, which might be an immunomodulatory target against the parasite infection." (PMID 30355335, 2018). "Lipopeptides are agonists for TLR2 and their ability to stimulate both cellular and humoural immune responses has been widely reported, but their use as adjuvants in vaccines for parasitic infections remains relatively unexplored." (PMID 26897363, 2016). "Interestingly, the TLR2 signaling can significantly suppress the development of the pre-erythrocytic stage of Plasmodium yoelii, as both liver parasite load and subsequent parasitemia were significantly elevated in both TLR2- and MyD88-deficient mice." (PMID 26667391, 2015).
parasitemia (continued). "As the T. cruzi bear several TLR-2 and -4 ligands and promote serum amyloid A production by macrophages, it is likely that during this parasite infection both signals cooperate to induce a proper environment for the induction of suppressor IL-10 producing neutrophils." (PMID 22577359, 2012). "Thus, in macrophages (and perhaps other innate immune cells), TLR2 dependent recognition of T. congolense triggers cytokine responses that may be critical for initiating protective adaptive immunity necessary for effective parasitemia control." (PMID 31824484, 2019). "In fact, TLR4 and TLR9 pathways, other than the TLR2 signal, can promote iNOS/NO production and play an important role in modulating injured livers from BALB/c and C57BL/6 mice during parasitic infection." (PMID 28784165, 2017). "Here we analyzed the requirement of TLR2 and TLR9 in the release of TNF-α, IL-12/IL-23p40 and IFN-γ, all present before the peak of parasitemia." (PMID 23650544, 2013). "Some members of the TLR family, such as TLR2 and TLR4, are involved in parasitic infections." (PMID 35927758, 2022). "However, TLR-2, the TLR whose inhibition increases parasite infection in HPE as well as parasite-induced tissue damage showed no significant increase in the microarray analysis." (PMID 30143027, 2018). "There was evidence showing that soluble egg antigens (SEA) from Schistosoma mansoni stimulated IL-10 production from B cells, and exclusively stimulated the upregulation of TLR-2 expression in B cells, suggesting a possible link between B10 and TLR-2 in parasite infection." (PMID 30355335, 2018). "In vitro stimulation of TLR2/6 by T. cruzi GPI-mucins leads to the production of pro-inflammatory cytokines such as IL-12 and TNF, as well as NO, which are related to a Th1-focused immune response that is important to control parasitemia and tissue parasitism." (PMID 29868507, 2018). "In conclusion, the alternative in the level of expression of TLR2 and TLR4 may imply the role of the innate immune system during parasitic infection." (PMID 27511368, 2016). "TLR2 does not affect the parasitemia and mortality, whereas TLR9 appears to be crucial for the control of parasite replication and mouse survival." (PMID 23650544, 2013). "While LB formation occurs through a toll-like receptor-2 (TLR2)-dependent mechanism as documented during T. cruzi infection in macrophages, the identification of downstream signaling pathways involved in this event during parasitic infections awaits further investigation." (PMID 27199996, 2016). "However, these authors observed no major difference in parasitemia and mortality between infected TLR2 knockout and wild-type mice." (PMID 21869919, 2012). "According to our data, the establishment of Th1 response depends on TLR9, but not on TLR2, which corroborates with evidence identifying the involvement of TLR9 in controlling parasitemia and survival during primary infection with T. cruzi." (PMID 23650544, 2013). "The objective of the study was to evaluate and compare serum antibody levels, Leishmania infantum specific IFN-γ production and TLR2 and TLR4 transcripts in non-stimulated blood from dogs with different clinical stages at the time of diagnosis as well as blood parasitemia." (PMID 29547503, 2018).
pulmonary fibrosis (29 papers, 2011 to 2025). Chronic progressive interstitial lung disorder characterized by the replacement of the lung tissue by connective tissue, leading to progressive dyspnea, respiratory failure, or right heart failure. "Moreover, the TLR2-JNK-AP-1 pathway also plays a crucial part in pulmonary fibrosis caused by Mycobacterium tuberculosis." (PMID 33015189, 2020). "TLR2 levels are elevated in pulmonary fibrosis, and inhibiting TLR2 expression can protect mice from bleomycin-induced lung injury and fibrosis." (PMID 39910395, 2025). "Consistently, lung fibrosis and the wet-to-dry weight ratio were ameliorated, with reduced inflammatory cytokine production in the TLR2−/− group." (PMID 37626060, 2023). "Fibroblast-specific deficiency of TLR4 is protective against fibrosis; however, mice deficient in TLR4, TLR2, and TLR9 exhibited aggravated pulmonary fibrosis." (PMID 36110858, 2022). "TLR2 signaling was reported to promote pulmonary fibrosis in a model of bleomycin-induced pulmonary fibrosis." (PMID 34376770, 2021). "In the bleomycin-induced pulmonary fibrosis model, TLR2 expression was detected in 29.5% (18/61) and 26.9% (21/78) of pulmonary nodose/jugular neurons and DRG neurons, respectively." (PMID 29518161, 2018). "The TLR2-MyD88-NF-κB pathway plays an important role in PC-mediated reduction in pulmonary fibrosis." (PMID 28725012, 2017). "Surprisingly, single deficiency of TLR2 in TLR2−/− mice reduced lung inflammation and damage upon intratracheal BLM administration leading to attenuated pulmonary fibrosis." (PMID 28836991, 2017). "LFA-1 has also been linked to cell signaling properties with various hyaluronan receptors, including the toll-like receptors (TLR2 and TLR4) and CD-44, which have been linked to the pathogenesis of interstitial pulmonary fibrosis." (PMID 25324695, 2014). "Polysaccharide A (PSA) produced by the human symbiont Bacteroides fragilis can induce Foxp3+ Tregs to produce IL-10 and TGF-β2 through Toll-like receptor 2 (TLR2) expression, thereby regulating inflammation and alleviating the progression of pulmonary fibrosis." (PMID 36274689, 2022). "Similarly, a previous study found that CPC reduced lung hydroxyproline levels as a biomarker for collagen deposition or fibrosis and had anti-fibrotic effects on bleomycin-induced pulmonary fibrosis in mice by mediating toll-like receptor 2 signaling pathway." (PMID 33407626, 2021). "The observed exacerbation of both, BLM and WTI-induced pulmonary fibrosis in TLR2−/−/TLR4−/− mice highlights that multiple and time-dependent signals seem to be required to shape an optimal immune response in order to orchestrate inflammation, resolution and regeneration." (PMID 28836991, 2017). "Thus, in contrast to the protective action of TLR4, TLR2 has disease-promoting effects in the acute model of BLM-induced pulmonary fibrosis." (PMID 28836991, 2017). "Considering a recent report that the loss of RAGE contributes to pulmonary fibrosis, the increase of HMGB1 in alveolar fluids itself may induce fibrogenesis through other HMGB1 receptors, such as the Toll-like family of receptors (TLRs), TLR4, TLR2, or TLR9." (PMID 21637372, 2011). "As discussed under the “TGFβ signaling pathway,” soluble decorin is an endogenous ligand to TLR2 and TLR4 and can activate the p38 MAPK and ERK pathways, promoting inflammation and lung fibrosis and acting as a DAMP." (PMID 36835058, 2023). "On the other end, in its soluble form, decorin is an endogenous ligand to TLR2 and TLR4 and can activate the p38 MAPK and ERK pathways, leading to pro-inflammatory signaling; it may also promote lung fibrosis when degraded by cathepsin-S because fragmentation disrupts its anti-fibrotic capabilities." (PMID 36835058, 2023).
pulmonary fibrosis (continued). "Here, we examined how the inhibition of multiple TLRs affects pulmonary fibrosis using a novel synthetic receptor activator of nuclear factor κB ligand (RANKL) partial peptide, MHP1-AcN, which could suppress TLR2, 3, 4, 7, and 9 signaling through CD14 and RANK." (PMID 35864207, 2022). "In one study, macrophages exposed to outer membrane vesicles from gram-negative bacteria released IL-17B through TLR2/4 sensing, subsequently inducing the secretion of chemokines and growth factor by alveolar epithelial cells, resulting in the development of pulmonary fibrosis." (PMID 34093523, 2021). "This suggests that PFD may mitigate silicosis progression through modulation of TLR2-mediated NF-κB p50/p65 pathway activation, consequently reducing TNF and MMP9 production-two critical mediators of inflammatory response and extracellular matrix remodeling in pulmonary fibrosis." (PMID 40470053, 2025).
ischemic stroke (28 papers, 2014 to 2025). A stroke disorder caused by obstruction of blood flow to the brain, due to thrombotic (local blood clot formation) or embolic (due to a blood clot or other material traveling from another site) event. "In a model of ischemic stroke, TLR2‐deficient mice have a smaller infarct volume and reduced inflammatory cell accumulation (monocyte/macrophage and activated microglia) in the ischemic hemisphere compared to WT mice." (PMID 37452512, 2023). "There are several reports showing that TLRs mediate ischemic brain injury and TLR2 deficient mice were protected against ischemic stroke." (PMID 26849209, 2016). "Increased TLR2 expression is associated with poor outcomes in patients with ischemic stroke." (PMID 37452512, 2023). "TLR2-deficient mice displayed decreased brain injury and leukocyte infiltration compared to wild-type (WT) mice, indicating a detrimental and proinflammatory role of TLR2 in ischemic stroke." (PMID 25879213, 2015). "Notably, TLR2-related pathways regulate microglia polarization, whereas NF-κB and p38 are implicated in the polarization shift of microglia/macrophages occurring after ischemic stroke." (PMID 36982872, 2023). "Twelve genes have been reported as potential regulators of HT in ischemic stroke in previous studies: Casp3, Csf2, Ctnnb1, Cxcl12, Hif1a, Il1b, Mtor, Ptgs2, Ptprc, Tlr2, Tlr4, and Vcam1." (PMID 40002863, 2025). "In ischemic stroke, TLR2 and TLR4 are particularly crucial in regulating microglia activation and play a key role in inducing neurodegeneration." (PMID 40746532, 2025). "Based on the results of immune infiltration and single-cell analysis, the exosome-related feature genes identified in this study (LGALS3, CD14, TLR2) regulate the neuroinflammatory process following ischemic stroke through multidimensional mechanisms." (PMID 40458459, 2025). "TLRs are essential for controlling the inflammatory response following ischemic stroke, as evidenced by the reduced levels of inflammatory cytokines and smaller infarct volumes seen in mice with genetic deletion of TLR2/4." (PMID 39649720, 2024). "Previous studies showed an upregulation of TLR2 and 4 following experimental ischemic stroke, while genetic deletion of TLR2, 4, and 9 attenuated tissue damage." (PMID 28912751, 2017). "This dual action—attenuating MyD88-dependent cytokine storms and stabilizing vascular integrity—aligns with ischemic stroke pathophysiology, particularly in subacute phases where controlled Tlr2 inhibition may balance inflammatory resolution and angiogenesis." (PMID 41354822, 2025). "TLR2 binds to HMGB1, an essential DAMP secreted by apoptotic neurons in the ischemic hemisphere that is associated with the severity of neurological impairment in ischemic stroke." (PMID 37452512, 2023). "As a result, TLR2 inhibition might be explored in the future as potential therapy against ischemic stroke." (PMID 35510663, 2022). "A persistent absence of TLRs may result in unwanted outcomes, as demonstrated by delayed exacerbation of an ischemic stroke despite reduced initial injury in TLR2 knockout mice." (PMID 33562802, 2021). "There is some controversy over the contribution of TLR2 to the outcome after ischemic stroke." (PMID 32264906, 2020). "Many studies have focused on the role of TLR2 and TLR4 in brain damage caused by ischemic stroke." (PMID 32746852, 2020). "In addition, HMGB1 (high-mobility group protein B1), released by injured endothelial and other cells following ischemic stroke, activates TLR2/4 which leads to ROS generation and cytokine production." (PMID 25036109, 2014). "Therefore, we investigated if and by which route (i. a., i. v., i. p.)pharmacological in vivo-TLR4-inhibition after ischemic stroke would protect against ischemic brain injury without the detrimental long-term effects observed in TLR2-deficient mice." (PMID 26849209, 2016). "TLR2, TLR4/MyD88/NF-κB, and AP-1 are important signaling pathways in the innate immune response to ischemic stroke." (PMID 39649720, 2024).
ischemic stroke (continued). "Many of the identified genes, including TLR2, TLR3, TLR9, GRN, COL1A1, FN1, and LAMB1, were reported as upregulated genes in previous reports of ischemic stroke." (PMID 35887140, 2022). "In mice experimental model with ischemic stroke, PBM therapy showed suppressed TLR-2 levels, MAPK signaling and NF-kB activation." (PMID 35111053, 2021). "The presence of several TLRs has been reported in the brain, both in glial and neuronal cells, and recent studies have reported the pathological roles of TLR2, TLR4 and TLR8 in ischemic stroke-induced brain injury." (PMID 25886362, 2015). "For example, in the classic TLR2/4 mice, after ischemic stroke, TLR2/4 binds to the endogenous ligand HMGB1, activating a series of signal transduction cascades, which then produce pro-inflammatory cytokines affecting the prognosis of ischemic stroke." (PMID 39649720, 2024). "Despite these studies implicating TLR2 in ischemic stroke, its role in ICH has not been elucidated thus far." (PMID 25879213, 2015).